RN7SKP161 (RN7SK pseudogene 161)
Gene: Miscellaneous RNA gene on chromosome 12 (10,084,186 to 10,084,490, forward strand). Ensembl gene ENSG00000223042.
Homologues: Orthologues: chimpanzee 7SK (98% identical), guinea pig 7SK (64% identical). Paralogues in human: 7SK (76% identical), RN7SKP211 (75% identical), RN7SKP180 (75% identical), RN7SKP79 (75% identical), RN7SKP246 (74% identical), RN7SKP71 (74% identical), RN7SKP90 (74% identical), RN7SKP150 (74% identical), RN7SKP176 (74% identical), RN7SKP203 (74% identical), RN7SKP255 (74% identical), RN7SKP47 (74% identical), and 283 more.